PTPRE (protein tyrosine phosphatase receptor type E)
Diseases named in the same sentence as PTPRE in open-access papers:
PTPRE is named in the same sentence as 42 diseases in open-access papers, as found by Europe PMC text mining. Sharing a sentence is not in itself a finding about the gene and the disease. The quoted sentences say what the papers report.
hepatocellular carcinoma (5 papers, 2015 to 2024). A malignant tumor that arises from hepatocytes. "PTPRE-depleted etoposide-resistant WERI-Rb1 cells did, however, not display significant changes in migration rates in ovo, contradicting findings that PTPRE promotes migration in macrophages and acts as a metastatic promoter in hepatocellular carcinoma." (PMID 38674157, 2024). "PTPRE protein levels were also reduced in human hepatoma (Huh) cells containing full length HCV RNA in replicons (FL) compared to parent Huh cells or Huh7 containing HCV replicons expressing only nonstructural proteins (NS)." (PMID 26421924, 2015). "Furthermore, PTPRE has been described as a downstream target of miR631 in hepatocellular carcinoma and an up-regulation and activation of PTPRE has been observed in MCF-7 cells and MDA-MB-231 upon stimulation with fibroblast growth factor (FGF)." (PMID 38674157, 2024). "PTPRE has been suggested as a direct downstream target of miR631 in hepatocellular carcinoma cells." (PMID 38674157, 2024). "Interestingly, PTPRE levels were lower in Huh7.5 and Huh7D human hepatoma cell lines compared to the Huh7 cell line that they were clonally derived from, and HCV replicates significantly higher in Huh7.5 and Huh7D cells compared to the parental Huh7 cell line." (PMID 28235043, 2017). "PTPRE was described as a downstream target of miR631 in hepatocellular carcinoma (HCC)." (PMID 38674157, 2024). "Thus, there is an association between reduced PTPRE levels and HCV replication in hepatoma cell lines in vitro and PTPRE levels are reduced in liver tissue from HCV infected people compared to HCV uninfected, suggesting that PTPRE may interfere with HCV replication by promoting Src-kinase signaling." (PMID 28235043, 2017).
breast carcinoma (3 papers, 2016 to 2024). "Further along this line, reduced PTPRE levels decreased the viability and anchorage-independent growth of human breast cancer cells." (PMID 38674157, 2024). "RB cells were reported to express all four known FGF receptors (FGFR;) and an up-regulation and activation of PTPRE was observed upon FGF stimulation of human breast cancer cells." (PMID 38674157, 2024). "Unexpectedly, silencing of PTPRE expression in human breast cancer cells has been shown to abolish ERK1/2 activation, leading to significantly diminished pERK levels and siPTPRE-transfected thyroid cancer cells likewise exhibited decreased pERK1/2 levels." (PMID 38674157, 2024). "Besides, PTPRE contributes to ERK1/2 and AKT activation in human breast cancer cells and in mice PTPRE antagonizes the activation of voltage-gated potassium channels by tyrosine kinases like Src." (PMID 38674157, 2024).
colorectal cancer (3 papers, 2008 to 2024). A primary or metastatic malignant neoplasm that affects the colon or rectum. "Our results provide evidence for frameshift mutations in six of these PTP genes (PTPN21, PTPRS, PTPN5, PTPN23, PTPRA, PTPRE) affecting about 32% of MSI-H colorectal cancers." (PMID 19000305, 2008).
lung adenocarcinoma (3 papers, 2016 to 2024). A carcinoma that arises from the lung and is characterized by the presence of malignant glandular epithelial cells. "In lung adenocarcinoma, PTPRE was suggested as one of the genes potentially helpful to categorize different prognostic and therapeutic subgroups." (PMID 38674157, 2024). "In kras mutant lung adenocarcinoma, the PTPRE is highly expressed, which can be used as a novel therapeutic target in kras mutant lung adenocarcinoma." (PMID 36341437, 2022).
asthma (2 papers, 2008 to 2024). "In summary, this study demonstrates that the G2D tool can be useful in the prioritization of candidate genes for a complex disease as it allowed us to find a novel asthma genetic association with the PTPRE gene in the SLSJ familial asthma sample." (PMID 18682798, 2008). "Among these, five (LPA, ADAM8, DOCK1, GPR123 and PTPRE) presented modest associations with asthma, atopy or allergic asthma." (PMID 18682798, 2008). "Considering that the PTPRE rs7081735 association to allergic asthma is the strongest in the SLSJ sample, we evaluated it in an independent familial cohort, the Childhood Asthma Management Program (CAMP)." (PMID 18682798, 2008). "Interestingly, a few genes such as NRM, PTPRE and SUZ12 were observed to be associated with Rheumatoid Arthritis, Asthma and Endometrial Stromal Sarcoma diseases, respectively, in humans and genes like SCNN1B associated with renal disease in cattle." (PMID 38674383, 2024). "Further work is needed to define the PTPRE possible role in asthma pathophysiology." (PMID 18682798, 2008).
rheumatoid arthritis (2 papers, 2024). A chronic, systemic autoimmune disorder characterized by inflammation in the synovial membranes and articular surfaces. "Genes like NRM, SLC6A6, and PTPRE are involved in Rheumatoid Arthritis, Myocardial Ischemia and Asthma diseases in humans." (PMID 38674383, 2024).
AA amyloidosis (1 paper, 2023). Secondary amyloidosis is a form of amyloidosis, that complicates chronic inflammatory disorders (mainly rheumatoid arthritis) and is characterized by the aggregation and deposition of amyloid fibrils composed of serum amyloid A protein, an acute phase reactant. "Future analyses of the WGS data of identified genomic regions should nonetheless include this gene to explore a possible link between PTPRE and systemic AA-amyloidosis." (PMID 38136948, 2023).
acute myeloid leukemia (1 paper, 2024). Acute myeloid leukemia (AML) is a group of neoplasms arising from precursor cells committed to the myeloid cell-line differentiation. "Upregulated levels of PTPRE have been found in several cancer entities, including acute myeloid leukemia and renal cell carcinoma." (PMID 38674157, 2024). "Expression of PTPRE was found to be significantly higher than average in acute myeloid leukemia (AML)." (PMID 38674157, 2024).
allergic asthma (1 paper, 2008). A asthma with a basis in a pathological type I hypersensitivity reaction. "PTPRE rs7081735 shows the strongest association to allergic asthma (p = 0.000463) and is the only SNP shown to be significant after multiple testing correction (corrected p = 0.0478)." (PMID 18682798, 2008). "The results suggest a protective association to allergic asthma for PTPRE rs7081735 in the SLSJ sample (p = 0.000463; corrected p = 0.0478)." (PMID 18682798, 2008). "Because the PTPRE association to allergic asthma remained significant after correction for multiple testing, we sequenced strategic regions around the rs7081735, aiming to find the causal mutation." (PMID 18682798, 2008). "After corrections for multiple testing, only the PTPRE rs7081735 association to allergic asthma remained significant." (PMID 18682798, 2008). "Thus, the positive association found for PTPRE rs7081735 and allergic asthma (p = 0.000463) remains significant when considering only those probands (Family number = 74; Z for the minor allele = −3.166; p = 0.001546)." (PMID 18682798, 2008). "Based on these observations, we conclude that the PTPRE rs7081735 association to allergic asthma is more penetrant in the SLSJ population, possibly resulting from an interaction with others genes and/or environmental factors that are more common in this founder population." (PMID 18682798, 2008). "Of these, one positive genetic association, resisting to corrections for multiple testing, has been found between the protein tyrosine phosphatase receptor type E gene (PTPRE) and allergic asthma in the SLSJ sample." (PMID 18682798, 2008).
alopecia (1 paper, 2019). Hair loss usually from the scalp. "The differential expression of WIF1, PTPRE, HBB, and LMCD1 is associated with hair loss, morphogenesis, and alopecia." (PMID 30993080, 2019).
amyloidosis (1 paper, 2023). A disorder characterized by the localized or diffuse accumulation of amyloid protein in various anatomic sites. "Nevertheless, PTPRE has not been reported in the context of amyloidosis and thus this assumption is speculative." (PMID 38136948, 2023).
androgenetic alopecia (1 paper, 2019). "Protein tyrosine phosphatase (PTPRE) and PHD finger protein 15 (PHF15) are differentially expressed in bald individuals responsible for androgenetic alopecia." (PMID 30993080, 2019).
bipolar disorder (1 paper, 2018). A disorder of the brain that causes unusual shifts in mood, energy, activity levels and the ability to carry out day-to-day tasks. "PrediXcan has been applied to bipolar disorder, resulting in the identification of two genes, PTPRE and BBX, for which predicted increased expression in whole blood and the anterior cingulate cortex, respectively, was associated with increased risk of bipolar disorder." (PMID 28847336, 2018).
childhood asthma (1 paper, 2008). "Even with the loss of statistical power due to the stratified analysis, this comparison allowed to assume that the association found for PTPRE is probably more related to a childhood asthma, comforting the choice of the CAMP cohort as a replication study." (PMID 18682798, 2008).
colon cancer (1 paper, 2016). "Co-expression analysis revealed that ACSL1 was coexpressed with MYBPH, PTPRE, PFKFB3, SOCS3 in colon cancer and with LRRFIP1, TSC22D1 in lung cancer." (PMID 27171439, 2016).
eye cancer (1 paper, 2024). "PTPRE plays a tumorigenic role in different human cancer cells, but its role in retinoblastoma (RB), the most common malignant eye cancer in children, remains to be elucidated." (PMID 38674157, 2024).
gastric cancer (1 paper, 2026). A primary or metastatic malignant neoplasm involving the stomach. "We found that PTPRE is upregulated in gastric cancer tissues and participates in the induction of 5-FU resistance." (PMID 42313735, 2026). "In summary, PTPRE suppresses ferroptosis in gastric cancer cells via the Src/FAK/TRIB3 signalling pathway, thereby inducing 5-FU resistance." (PMID 42313735, 2026). "Mechanistic studies revealed that PTPRE suppressed ferroptosis in gastric cancer cells and promoted 5-FU resistance by activating the Src/FAK pathway to upregulate TRIB3 expression." (PMID 42313735, 2026). "Intervention with PTPRE and its downstream targets may represent a potential approach for the clinical treatment of 5-FU-resistant gastric cancer." (PMID 42313735, 2026). "Therefore, we analysed PTPRE expression in gastric cancer using The Cancer Genome Atlas." (PMID 42313735, 2026). "The protein tyrosine phosphatase receptor type E (PTPRE) plays an oncogenic role in certain tumours; however, its function in chemotherapy-resistant gastric cancer remains unclear." (PMID 42313735, 2026).
liver cancer (1 paper, 2022). An epithelial or non-epithelial malignant neoplasm that arises from the liver. "Studies have shown that in primary liver cancer, miR-631 can target the receptor protein tyrosine phosphatase gene (PTPRE) to inhibit the intrahepatic metastasis of liver cancer." (PMID 36341437, 2022).
lymph node metastasis (1 paper, 2024). "It has been shown, that the promoter methylation status of PTPRE is strongly associated with lymph node metastasis (LNM) of papillary thyroid carcinoma (PTC) and high expression correlates with a significantly better survival." (PMID 38674157, 2024).
neuroblastoma (1 paper, 2021). Neuroblastoma (NB) is the most common solid, extracranial childhood tumor. "PTPRA is highly expressed in SH-SY5Y neuroblastoma cells, whereas the related PTPRE (RPTPε) is expressed at low levels but induced upon retinoic acid differentiation." (PMID 34957126, 2021). "The possibility exists that the use of PTPRA/PTPRE inhibitors could complement the use of Src inhibitors in neuroblastoma therapies." (PMID 34957126, 2021).
Obesity (1 paper, 2016). Accumulation of substantial excess body fat. "A potential causal role for metabolic differences under similar obesity state was detected for PTPRE, IL-6R and SLC6A5." (PMID 27907186, 2016).
osteoporosis (1 paper, 2021). A condition of reduced bone mass, with decreased cortical thickness and a decrease in the number and size of the trabeculae of cancellous bone (but normal chemical composition), resulting in increased fracture incidence. "In the PTPRE gene drug binding domain for alendronate (indicated for osteoporosis), we identify a variant (chr10:129868686) in Roma (3.7%), virtually absent in non-Roma, except GIH (0.5%)." (PMID 34220960, 2021).
papillary thyroid carcinoma (1 paper, 2024). "Since an epigenetic regulation of PTPRE via promotor methylation has been described for pituitary adenomas and papillary thyroid carcinoma, we performed PTPRE promotor methylation analyses for the etoposide-resistant RB cell lines Y79 and WERI and their chemosensitive counterparts." (PMID 38674157, 2024).
pituitary adenomas (1 paper, 2024). "Promoter hypermethylation and decreased expression level of PTPRE were described for nonfunctioning pituitary adenomas (NFPAS), whereby invasive and non-invasive NFPAs displayed only slight differences in their methylation profiles." (PMID 38674157, 2024).
renal cell carcinoma (1 paper, 2024). "Overexpression of PTPRE was likewise reported for all stages of renal cell carcinoma." (PMID 38674157, 2024).
thyroid cancer (1 paper, 2024). "It has been shown that PTPRE expression in murine mammary glands leads to massive hyperplasia and associated tumorigenesis and high PTPRE expression in thyroid cancer correlates with tumor size." (PMID 38674157, 2024). "Upregulated PTPRE has been shown to promote cell proliferation, whereas PTPRE KD resulted in the opposite effect indicating an oncogenic function in thyroid carcinoma." (PMID 38674157, 2024). "Besides, PTPRE is highly expressed in thyroid cancer clinical samples and cell lines and overexpression correlates with the TNM stage." (PMID 38674157, 2024).
cancer (7 papers, 2014 to 2024). A tumor composed of atypical neoplastic, often pleomorphic cells that invade other tissues. "Abnormal promoter hypermethylation and low expression of PTPRE have been linked to cancer development, suggesting the protective role of PTPRE overexpression." (PMID 38172938, 2024). "In addition, the PTPRE depletion also led to a re-sensitization of the resistant RB cell lines towards etoposide, underlining its potential role in cancer cell transformation processes." (PMID 38674157, 2024). "It’s reported that in hepatocytes and liver, PTPRE inactivates insulin receptor signaling, which might influence both risk and prognosis in many kinds of cancers." (PMID 33344226, 2020). "PTPRE has been studied, e.g., in osteoclasts, nerve cells, and cancer cells, and it exerts different functions among various tissues (for review see:)." (PMID 38674157, 2024). "It has been shown that promoter methylation is an important mechanism to regulate PTPR expression (for review;) and aberrant PTPRE promoter methylation has been observed in various cancers." (PMID 38674157, 2024). "As small molecules and antibodies inhibiting the activity of tyrosine kinases are effective tools in cancer treatment, regulators of tyrosine kinase activity like the tyrosine phosphatase PTPRE hold the potential of new future RB therapy targets." (PMID 38674157, 2024). "It has been shown that many cancer entities are connected to aberrant activation of tyrosine kinases, including PTPRE." (PMID 38674157, 2024). "Studies of PTPRE signaling in cancer in general and in RB in particular will help to develop novel RB treatment strategies targeting this tyrosine phosphatase and its up- and downstream signaling components." (PMID 38674157, 2024). "In addition, it had been reported that PTPRE could act as an oncogene in some kind of cancers, indicating it had an opposite function with miR-631." (PMID 33344226, 2020). "It is interesting to note that PTPRE is coexpressed with ACSL1 and ACSL5 in cancer, which warrants further investigation." (PMID 27171439, 2016).
tumor (7 papers, 2008 to 2026). "Summarizing, one can state that PTPRE acts as an oncogene in RB and is most likely involved in chemotherapy resistance mechanisms by enhancing cell proliferation and tumor growth and inhibiting apoptosis." (PMID 38674157, 2024). "In vivo chicken chorioallantoic membrane (CAM) assays revealed decreased tumor formation capacity as well as reduced tumor size and weight following PTPRE KD." (PMID 38674157, 2024). "MiR631 targets genes, including PTPRE, are involved in different cellular processes including proliferation, apoptosis, invasion, and drug resistance and sensitivity, therefore playing an important role in tumor progression (for review see:)." (PMID 38674157, 2024). "To investigate whether the effects of a PTPRE knockdown on etoposide-resistant RB cell growth in vitro likewise influence their tumor growth and migration potential in vivo, we used the chicken in ovo chorioallantoic membrane (CAM) assay as a model system." (PMID 38674157, 2024). "Data gained by our analyses revealed decreased cell viability and tumor development as well as re-sensitization towards etoposide upon PTPRE KD in RB cells, indicating an oncogenic role of PTPRE in chemoresistant retinoblastoma, involving miR631 and SGK3 regulating mechanisms." (PMID 38674157, 2024). "The activity of SRC is significantly reduced in tumor cells lacking PTPRE and restoring SRC activity revealed that it is only its reduced activity that caused aberrant proliferation rates of tumor cells lacking PTPRE." (PMID 38674157, 2024). "In accordance with these findings, in our study presented, PTPRE-depleted, etoposide-resistant RB cells developed significantly smaller tumors in ovo than control cells, supporting the notion of PTPRE being an oncogene rather than a tumor suppressor in RB." (PMID 38674157, 2024). "We, therefore, estimated the roles of classical PTPs in anti-PD-L1 treatment and found that seven PTPs were significantly higher in the non-responsive tumor, including PTPN12 and PTPRE." (PMID 36341348, 2022).
infection (1 paper, 2017). The state of being infected such as from the introduction of a foreign agent such as serum, vaccine, antigenic substance or organism. "Since HCV replicates primarily in hepatocytes during human infection, we examined PTPRE levels in liver explant tissues obtained from HCV-infected and HCV-uninfected individuals." (PMID 28235043, 2017). "Furthermore, serum-derived HCV RNA present in virions or serum extracellular vesicles are transferred into hepatocytes and lymphocytes resulting in reduced PTPRE protein levels and productive infection in vitro." (PMID 28235043, 2017).
PTPRE also shares sentences with these, for which no sentence is quoted: Alzheimer disease (1 paper); autistic disorders (1); Chronic Lymphocytic Leukemia (1); diabetes (1); fibrosis (1); Glycogen Storage Disease (1); leukaemia (1); liver disease (1); lung carcinoma (1); melanoma (1); myocardial ischemia (1); osteoarthritis (1); renal disease (1).